LEP (leptin)
Diseases named in the same sentence as LEP in open-access papers (continued):
Sharing a sentence is not in itself a finding about the gene and the disease.
osteoporosis (continued). "However, other studies have shown that excess weight in children is associated with elevated levels of leptin and parathyroid hormone (PTH), both of which may enhance bone resorption and increase the risk of osteoporosis and fractures." (PMID 40566375, 2025). "However, the dysregulation of leptin levels, whether increased or decreased, can disrupt this balance, potentially contributing to the pathogenesis and progression of osteoporosis." (PMID 41326350, 2025). "However, high leptin levels are negatively correlated with osteoporosis, as leptin’s pro-inflammatory effects may increase bone resorption." (PMID 39897963, 2024). "Firstly, osteoporosis caused by db/db mice is mainly related to the changes in the endogenous hormone leptin level, which may not be applicable to patients with T2DOP caused by other pathological factors." (PMID 38191438, 2024). "In the present study, the number of osteoclasts was significantly reduced after leptin overexpression in Sema4D-overexpressed OVX rats, which further verified that the improvement effect of leptin on osteoporosis might be related to the inhibition of osteoclast activation." (PMID 37031174, 2023). "Leptin may have a therapeutic role in treating osteoporosis in undernourished patients." (PMID 22518129, 2012). "However, leptin acts through the inhibition of bone formation and this is not the major cause of bone loss in post-menopausal osteoporosis." (PMID 22115044, 2011). "In postmenopausal women, significantly lower leptin (SMD = -0.88) and higher adiponectin (SMD = 0.94) levels were seen in the osteoporosis group than in the control group." (PMID 37181034, 2023). "Research also showed that resistin, leptin, IL-1, IL-4, IL-6, and TGF-β played a significant role in postmenopausal women’s bone metabolism and could be used as a diagnostic marker capable of recognizing patients at risk of osteoporosis and thereby predicting the risk of fracture." (PMID 33519717, 2020). "The level of H2S in the plasma was determined and common laboratory indicators to diagnose osteoporosis, such as alkaline phosphatase (ALP) activity and the levels of osteocalcin (OCN), calcitonin, parathyroid hormone and leptin were measured." (PMID 30305826, 2018). "Leptin levels were lower in men with obstructive pulmonary disease and osteoporosis than in those without osteoporosis." (PMID 40076690, 2025). "Despite the decrease observed in cholestatic patients, not all hepatic diseases lead to suppressed leptin levels, and clear data on its role in osteoporosis are still lacking." (PMID 27840821, 2016). "Our results indicate the effect of propranolol on ovariectomy-induced osteoporosis may be exerted, at least partly, through the regulation of leptin signaling and there may be an interaction between the SNS and leptin on the regulation of bone metabolism." (PMID 24250662, 2013). "Furthermore, the COPD patients with osteoporosis had lower leptin levels compared to those without osteoporosis." (PMID 40076690, 2025). "Marrow fat secretes several adipokines, such as Leptin, Adiponectin, TNFα, IL1β, and IL6, which promote chronic inflammatory responses and are shown to be highly correlated with bone cancer metastasis and markers for the progression of bone diseases such as osteoporosis." (PMID 39056808, 2024). "Therefore, we proposed the hypothesis that Zhuang-Gu-Fang may interfere with the process of bone metabolism by regulating Leptin, Ghrelin, and PYY to prevent osteoporosis further." (PMID 33281915, 2020). "In addition, leptin influences bone metabolism via the SNS, indicating that Adrb antagonists, which are commonly utilized for treating cardiovascular conditions, might have therapeutic benefits for osteoporosis." (PMID 39165638, 2024).
osteoporosis (continued). "Middle-aged and elderly individuals with lower skeletal muscle function and BMD had higher expression levels of LEP, ADIPOQ, RBP4, DPP4 and inflammatory markers, suggesting that adipokines may play a role in the activation of inflammation and lead to the development of sarcopenia and osteoporosis." (PMID 37525169, 2023).
sarcopenia (65 papers, 2011 to 2025). Progressive decline in muscle mass due to aging which results in decreased functional capacity of muscles. "A number of reports showed that elevated levels of serum leptin and other inflammatory cytokines were linked with lower skeletal muscle mass and a higher risk of sarcopenia." (PMID 40001498, 2025). "Regarding metabolic biomarkers, body mass index (BMI) and leptin showed inverse associations with sarcopenia, whereas adiponectin and high-density lipoprotein (HDL) showed positive correlations." (PMID 41568005, 2025). "In summary, leptin is involved in the adipose tissue–muscle axis, implicated in the pathogenesis of sarcopenia and cachexia." (PMID 39764565, 2025). "A prospective cross‐sectional cohort study showed that the circulating level of leptin was significantly elevated in the sarcopenia group and correlated with sarcopenia incidence, sarcopenia severity, and sarcopenia risk." (PMID 39764565, 2025). "In a cross-sectional study of 4,062 subjects (≥69 years old), serum leptin levels were found to be associated with the risk of obesity-related sarcopenia." (PMID 40801027, 2025). "The blood leptin level is reported to have a positive correlation with the risk of dynapenia, whereas the serum leptin level negatively correlates with the risk of sarcopenia in both female and male aged people." (PMID 37815907, 2024). "Sarcopenia is linked to the adipokines, i.e., leptin and adiponectin, which are secreted by adipose and musculoskeletal tissues." (PMID 36498747, 2022). "Sarcopenia status and reduction were associated with blood biomarkers related to muscle metabolism, steroid hormone regulation, insulin-leptin signaling, and tissue oxygenation." (PMID 33882026, 2021). "In our study, we found that an increased adiponectin:leptin ratio was associated with faster walking speed (though this association was not robust beyond gender-adjustment) and with reduced risk of sarcopenia." (PMID 29101476, 2018). "Previous studies investigating the association between leptin and sarcopenia have been inconclusive." (PMID 21931785, 2011). "This relationship may explain why leptin, in addition to its association with muscle mass, was also found to be negatively associated with muscle strength and with the risk of sarcopenia." (PMID 40001498, 2025). "Higher leptin levels are associated with a higher risk of sarcopenia in the elderly." (PMID 40801027, 2025). "Sarcopenia has been associated with high adiponectin and low leptin levels." (PMID 38632706, 2024). "Our results of lower leptin level in sarcopenic older individuals corroborate the findings of previous studies which demonstrated an inverse association between serum leptin level and sarcopenia in hemodialysis patients." (PMID 36482911, 2022). "Furthermore, fasting insulin, C-peptide, and leptin were significantly associated with one or more clinical and functional measures of sarcopenia and frailty including total body mass, muscle mass, knee extension strength, gait speed, and physical activity." (PMID 36482911, 2022). "However, the frail elderly with high prevalence of low lean mass defined as sarcopenia have low leptin levels and higher leptin levels are associated with increased longevity in centenarians, suggesting a role for leptin in skeletal muscle metabolism." (PMID 29949600, 2018). "Given that these factors are known to play roles in development of sarcopenia, leptin may also play a causative role in development of sarcopenia." (PMID 21931785, 2011). "Moreover, it has been reported that leptin can increase muscle mass by reducing the expression of atrophy-associated factors, including MuRF1, myostatin, and MAFbx, in muscles, indicating that leptin is significantly related to sarcopenia severity and risk." (PMID 37153220, 2023). "Elevated levels of adipokines, such as leptin and interleukin-6, can impair muscle function and contribute to the progression of sarcopenia." (PMID 41403750, 2025).
sarcopenia (continued). "We selected myonectin, Metrnl, adiponectin (ApN), and leptin, which are more related to aging sarcopenia." (PMID 40801027, 2025). "A similar relationship was also observed between the leptin and sarcopenia parameters (muscle strength and mass), as well as in the bone health parameters (bone mineral density and t-score)." (PMID 39599699, 2024). "On the other hand, it has been discovered that leptin, a factor derived from adipose tissue, can promote the synthesis of inflammatory cytokines, thus playing a role in the development of sarcopenia." (PMID 38628269, 2024). "In comparison with the Fit phenotype, patients with the Overweight/Obese and Sarcopenia/Obese phenotypes had significantly increased abundance of leptin." (PMID 39575261, 2024). "For patients with the Sarcopenia/Obese phenotype versus Fit phenotype, we noted significantly increased abundance of leptin and significantly decreased abundance of adiponectin." (PMID 39575261, 2024). "Leptin-induced inflammation and elevation in cytokines, such as IL-6 and TNF-α, correlated with an enhanced risk of sarcopenia." (PMID 39229323, 2024). "Blood was drawn, and inflammatory biomarkers associated with Sarcopenia (IL-2, IL-4, IL-5, IL-6, IL-8, IL-10, TNF, adiponectin, leptin, resistin, BDNF, sTNFr-1 and sTNFr-2) was analysed." (PMID 37365209, 2023). "Leptin, an adipokine secreted by adipose tissue, promotes the production of pro-inflammatory cytokines, which in turn lead to sarcopenia." (PMID 35892736, 2022). "Exercise studies have shown that 12 weeks of resistance training reduces plasma leptin and resistin levels, and concluded that long-term resistance training improves sarcopenia in people by reducing inflammatory markers and reducing adipose tissue." (PMID 35250869, 2022). "Only GNRI was related to leptin change largely due to the main constituents of this index, i.e., albumin and body weight, and due to the better performance in detecting sarcopenia." (PMID 34441040, 2021). "Studies have discussed changes of leptin levels in sarcopenia patients, and recognized its role in aging muscle." (PMID 34782007, 2021). "Body composition analysis through DXA, CHI, lean psoas area, or measured leptin levels can augment BMI through the identification of sarcopenia in overweight/obese patients or higher than anticipated lean muscle mass in underweight patients." (PMID 31783495, 2019). "Logistic regression analysis is used to obtain odds ratio in the presence of the explanatory variable (serum leptin and adiponectin levels) for sarcopenia in both males and females." (PMID 31703113, 2019). "Plasma leptin levels are increased in individuals with sarcopenia and visceral obesity compared to those with sarcopenia or visceral obesity alone." (PMID 31077169, 2019). "Further, in both men and women, leptin levels were found to be higher in subjects with both thigh muscle sarcopenia and visceral obesity or being overweight than in those with only one abnormality." (PMID 21931785, 2011). "After correction for fat mass, these authors noted higher concentrations of leptin among subjects with sarcopenia than those with sarcopenic obesity." (PMID 21931785, 2011). "Plasma levels of leptin were higher in subjects with sarcopenic visceral obesity than in those with either sarcopenia or visceral obesity alone." (PMID 21931785, 2011). "In addition, it has been shown that leptin levels are higher in patients with sarcopenic visceral obesity than in patients with sarcopenia alone." (PMID 40392885, 2025). "Interestingly, serum adiponectin was significantly increased but the ratio of leptin/adiponectin was dramatically decreased in the RA patients with sarcopenia." (PMID 38602220, 2024). "However, there are discrepancies in several other studies explaining the protective or irrelevant role of leptin in sarcopenia." (PMID 39229323, 2024). "Adipokines, including leptin, adiponectin, resistin, and apelin play crucial roles in sarcopenia." (PMID 38602220, 2024).
sarcopenia (continued). "The impact of SCI-induced sarcopenia on leptin signaling within skeletal muscle and systemically is unknown." (PMID 29949600, 2018). "Lower adiponectin:leptin ratios and elevated levels of CRP, cortisol and IL-8 were associated with increased risk of sarcopenia as defined by the EWGSOP algorithm at follow-up, although the strength of associations varied according to the other covariates included in the models." (PMID 29101476, 2018). "Measuring leptin may have value for BMI correction, predicting increased medical comorbidities related to hyperleptinemia and sarcopenia (including, but not limited to some cancers), and permanent weight loss." (PMID 22485140, 2012). "Given that leptin has been hypothesized to be involved in the pathogenesis of sarcopenic obesity, we investigated the relationship between plasma leptin levels and thigh muscle sarcopenia and visceral obesity." (PMID 21931785, 2011). "Another study of community-dwelling older adults showed a positive association of leptin serum levels with muscle and fat mass and negative with muscle strength—increased leptin levels were linked to a higher risk of dynapenia (low muscle strength), but a lower risk of sarcopenia." (PMID 38398421, 2024). "Sarcopenia was associated with lower leptin level than the non-sarcopenia group." (PMID 36482911, 2022). "In addition, a study indicated that leptin is a linkage between visceral obesity and sarcopenia." (PMID 36297085, 2022). "Currently, it is unclear whether leptin and muscle mass or sarcopenia interact." (PMID 36498747, 2022). "Collectively, ghrelin and leptin may bridge H. pylori and sarcopenia altogether." (PMID 34782007, 2021). "Finally, CRP and IL-8 levels and adiponectin/leptin ratio may have prognostic value for the development of sarcopenia." (PMID 33566325, 2021). "The study found that, compared with those in non-sarcopenia patients, the serum levels of IL-6, IL-18, TNF-α, TNF-like weak inducing factor of apoptosis (TWEAK), and leptin were significantly increased in sarcopenia patients." (PMID 37584041, 2023). "Therefore, leptin resistance may worsen sarcopenia in obese and elderly patients." (PMID 35250869, 2022). "The slope of leptin was diagonally upward, whereas the adiponectin was diagonally downward; meanwhile, in the control group, the changes in adiponectin normalized by BMI and BFM of the frail and sarcopenia groups were noticeable." (PMID 38602220, 2024). "Considering another component of sarcopenia in patients with PDAC, it has been proven that increased TNF-α and IL-1 concentrations lead to excessive transcription of leptin mRNA, resulting in higher serum leptin concentrations in patients with PDAC and decreased appetite." (PMID 39458563, 2024). "The leptin/BMI level in RA patients with sarcopenia was lower when compared with those RA patients without sarcopenia." (PMID 38602220, 2024). "Intriguingly noted, the leptin/adiponectin ratio was lowest in the RA patients with sarcopenia than in the RA patients without and those with frailty." (PMID 38602220, 2024). "The leptin/BFM was increased in all RA patient groups and in those controls with sarcopenia." (PMID 38602220, 2024). "In females, neither adiponectin nor leptin level was an independent predictive factor (p = 0.955 for adiponectin: p = 0.405 for leptin) for sarcopenia, adjusted by age." (PMID 31703113, 2019). "Our findings of lower leptin levels in those with sarcopenia versus those with normal muscle mass suggests that intramuscular fat is not the primary source of muscle-derived leptin." (PMID 29949600, 2018). "Furthermore, serum leptin concentrations in the sarcopenia group were not elevated as compared with the non-sarcopenic group." (PMID 40647619, 2025).
sarcopenia (continued). "The leptin/BMI level exponentially increased in the control group with frailty and further in those with sarcopenia, while the leptin/BMI level in the RA patients without frailty nor sarcopenia, was higher than those sarcopenia patients in the control group." (PMID 38602220, 2024). "Leptin, secreted by adipose tissue, acts as a pro-inflammatory hormone; serum levels of leptin are higher in subjects with SO, rather than in those with either sarcopenia or visceral obesity alone." (PMID 34858322, 2021). "As HGS is a marker of muscle mass and alongside bioimpedance-derived evidence for muscle mass loss after kidney transplantation in study subjects, we suppose that leptin association with GNRI, but not SGA or MIS, could be explained by better GNRI performance in detecting sarcopenia." (PMID 34441040, 2021).